LRIG1 (leucine rich repeats and immunoglobulin like domains 1)
Diseases named in the same sentence as LRIG1 in open-access papers (continued):
Sharing a sentence is not in itself a finding about the gene and the disease.
glioma (continued). "LRIG3 was, in contrast to LRIG1 and LRIG2, significantly increased in glioma compared to control tissue (1.354 ± 0.89 vs. 0.746 ± 0.242, p = 0.039), with highest difference to grade II glioma (1.556 ± 0.702 vs. 0.746 ± 0.242, p = 0.0.0002)." (PMID 41201961, 2025). "The level of another microRNA, miR-590-3p, was increased in glioma tissues and radioresistant glioblastoma cells; miR-590-3p was shown to promote radioresistance by directly inhibiting the tumor suppressor LRIG1 (leucine rich repeats and immunoglobulin like domains 1)." (PMID 35846075, 2022). "LRIG1 is a potent inhibitor of GBM growth in clinically-relevant experimental glioma models, largely independent of EGFR status and is thought to restrict proliferation and aggressiveness of GSCs." (PMID 36420140, 2022). "Since miR‐19 might negatively regulate EGFR via LRIG1, the impact of EGFR on invasion and angiogenesis of glioma cell may be connected with miR‐19." (PMID 30073755, 2018). "The non-physiological overexpression of LRIG1 has been shown to inhibit the proliferation of certain glioma cell lines in vitro." (PMID 29391393, 2018). "Recent study demonstrated that microRNA-19a promotes gliomas cell growth by repressing LRIG1 which is a pan-negative regulator of membrane-bound receptor tyrosine kinases(RTKs)." (PMID 29340016, 2017). "Therefore, we could examine the expression of genes LRIG1 and ZNF703 in the glioma and normal tissue samples." (PMID 38790164, 2024). "Moreover, soluble extracellular part of mouse Lrig1 is capable of inhibiting glioma growth in vitro and in vivo irrespective of EGFR status." (PMID 25353163, 2014). "LRIG1 regulates EGFR, and its soluble form has been shown to inhibit in vivo glioma growth irrespective of EGFR status." (PMID 31842352, 2019).
breast carcinoma (25 papers, 2005 to 2025). "This includes breast cancer, where low LRIG1 expression has been linked to decreased relapse-free, and distant metastasis-free, survival." (PMID 35440669, 2022). "Conversely, restoration of LRIG1 expression provokes a mesenchymal-to-epithelial transition, as well as loss of tumorigenic and invasiveness potentials of highly invasive basal breast cancer cells." (PMID 34359928, 2021). "The identification of prognostic markers for risk of relapse in breast cancer is of major importance, and loss of LRIG1 has indeed been shown to be a strong candidate marker for the risk of relapse in a stage I-II American breast cancer cohort." (PMID 32448168, 2020). "LRIG1 copy number ratios were associated with the breast cancer subtype, steroid receptor status, ERBB2 status, tumor grade, and nodal status." (PMID 32448168, 2020). "Among 423 stage I-IV breast cancer cases with a long follow-up period (20 years), we investigated possible associations between LRIG1 copy number and patient survival and various clinical factors." (PMID 32448168, 2020). "For example, LRIG1 expression is decreased in renal cell carcinoma, while high LRIG1 expression is associated with an improved prognosis in breast cancer, early stage invasive squamous cervical cancer and cutaneous SCC." (PMID 25013483, 2014). "We propose that a common, but hitherto unrecognised, breast cancer linked gene is located within an amplicon containing the LRIG1 locus at 3p14.3." (PMID 16168117, 2005). "To explore whether LRIG1 expression was associated with survival, we used the KMplotter webtool, with 4929 patients with breast cancer informative for RFS and 1879 patients informative for OS in the mRNA gene chip setting." (PMID 37930698, 2023). "Thereby, we could confirm some and refute other previously published observations regarding LRIG1 copy number associations in breast cancer." (PMID 32448168, 2020). "Importantly, LRIG1 loss was recently shown to predict early and late relapse in stage I-II breast cancer." (PMID 32448168, 2020). "Interestingly, a contrast to what we found in bladder cancer, LRIG1 was shown to be associated with good survival in 7 types of cancers such as breast cancer, uterine cervical cancer, and head-and neck cancer etc." (PMID 32065779, 2020). "Moreover, LRIG1 loss increases the risk of early and late relapse of breast cancer, but its overexpression inhibits EMT and cell invasion." (PMID 30487162, 2019). "LRIG1 encodes a protein that acts as a growth suppressor in breast cancer." (PMID 20334636, 2010). "We next examined the correlation between LRIG1 CpG island methylation and LRIG1 mRNA read count in breast cancer (n = 784)." (PMID 35440669, 2022). "Having examined publicly available patient samples, we next examined LRIG1 CpG island methylation in breast cancer cell line models." (PMID 35440669, 2022). "We previously reported that LRIG1 expression is lowest in the basal-like molecular subtype of breast cancer." (PMID 35440669, 2022). "Silencing of LRIG1 through promoter CpG island methylation has been reported in colorectal and cervical cancer but studies in breast cancer remain limited." (PMID 35440669, 2022). "In silico analysis of human breast cancer patient data were used to demonstrate a correlation between DNA methylation and LRIG1 silencing in basal/triple-negative breast cancer, and its impact on patient survival." (PMID 35440669, 2022). "As an ERα target gene, LRIG1 is most highly expressed in ER-positive luminal disease relative to other breast cancer subtypes, with the lowest expression observed in basal/triple-negative breast cancers (TNBC)." (PMID 35440669, 2022). "To determine if this pattern also exists in the larger TCGA-BRCA dataset, we examined LRIG1 expression as a function of breast cancer molecular subtypes." (PMID 35440669, 2022).
breast carcinoma (continued). "In contrast, LRIG1 gene expression was found enriched in ERα-positive breast cancer, and consistently, LRIG1 has proven to be a transcriptional target of ERα." (PMID 34359928, 2021). "Leucine-rich repeats and immunoglobulin-like domains 1 (LRIG1) copy number alterations and unbalanced gene recombination events have been reported to occur in breast cancer." (PMID 32448168, 2020). "By using a novel ddPCR-based LRIG1 copy number assay, we have shown that LRIG1 loss is associated with nodal status and other clinical parameters; however, we could not verify LRIG1 loss as a robust independent predictor of the risk of relapse in breast cancer." (PMID 32448168, 2020). "This outcome mirrors the results of a previous study, which showed that LRIG1 overexpression inhibited the migration of the breast cancer cell lines MDA-MB-157 and MDA-MB-231, at least in part, by inhibiting MET30." (PMID 29391393, 2018). "Accordingly, the expression levels of ESR1 and LRIG1 were correlated in breast cancer (Spearman's correlation coefficient, 0.56), other cancers, and many normal tissues." (PMID 29317492, 2018). "RIF1 detected LRIG1, a gene that is known to correlate with relapse-free survival in ERα-positive breast cancer." (PMID 29741575, 2018). "LRIG1 is down-regulated in several cancers and cancer cell lines, including breast cancer and squamous cell carcinoma of the skin and uterine cervix, where low LRIG1 expression correlates with poor patient survival." (PMID 22554477, 2012). "Consistent with its role in ErbB receptor degradation in vitro, Lrig1 is deleted in several different forms of human cancers, and low expression of Lrig1 correlates with poor prognosis of cervical and breast cancer." (PMID 20126551, 2010). "We conclude, nevertheless, that a common but hitherto unrecognised breast cancer gene is located at or near the LRIG1 locus." (PMID 16168117, 2005). "We report an unexpected increase in copy number of the LRIG1 locus in 39% of the breast tumours, implicating a breast cancer gene at, or close to, 3p14.3." (PMID 16168117, 2005). "The present study was conducted to investigate if the LRIG1 gene, mRNA, or protein was deleted or dysregulated in human breast cancer." (PMID 16168117, 2005). "Accordingly, the presented results imply that a common, but hitherto unrecognised, breast cancer related gene was located within an amplicon that included the LRIG1 locus at 3p14." (PMID 16168117, 2005). "This novel investigation of 3p14 demonstrated unexpectedly an increased copy number of the proposed tumour suppressor gene LRIG1 in 39% (11/28) of the breast tumours and in 60% (3/5) of the breast cancer cell lines." (PMID 16168117, 2005). "Because EGFR/ERBB1 and ERBB2 are important and frequently overexpressed breast cancer genes, it is unlikely that LRIG1, as an ERBB antagonist, is a tumour promoter." (PMID 16168117, 2005). "The molecular function of LRIG1 as a negative regulator of ERBB receptors questions the biological significance of increased LRIG1 copy number in breast cancer." (PMID 16168117, 2005). "Because ERBB family members are strongly implicated in the aetiology of breast cancer, and because ERBB proteins and LRIG1 interact at the molecular level, we analysed the expression of EGFR/ERBB1 and ERBB2 mRNA." (PMID 16168117, 2005). "In a different study, miR-218-5p was found to have supported the ERBB2 and EGFR expression by inhibiting the LRIG1 in breast cancer cells, which shows that miR-218-5p, and LRIG1can act as an oncogene in breast cancer and can be used as a therapeutic target for breast cancer treatments." (PMID 38954213, 2025). "Moreover, gene LRIG1 has a crucial role in some other cancer types such as bladder cancer, colorectal cancer, breast cancer, and lung cancer." (PMID 38790164, 2024). "Across breast cancer subtypes, LRIG1 expression is lowest in the basal/triple-negative subtype so we investigated whether differential methylation may contribute to this." (PMID 35440669, 2022).
breast carcinoma (continued). "However, genetic alterations in LRIG1, such as copy number variation, are observed in less than 1% of breast cancers, indicating that epigenetic silencing is a dominant mechanism of LRIG1 loss." (PMID 35440669, 2022). "LRIG1 mRNA and protein are consistently decreased across cancer types, including breast cancer." (PMID 35440669, 2022). "The mechanisms which contribute to LRIG1 downregulation in breast cancer are not fully understood but are known to include ERBB2-mediated repression and loss of gene copy number, which conveys persistent risk of relapse in patients typically considered low-risk." (PMID 35440669, 2022). "To examine whether LRIG1 is methylated in breast cancer, we utilised the publicly available TCGA-BRCA dataset, useful for both its large sample size and matched patient methylation-mRNA expression data." (PMID 35440669, 2022). "We used ADC, a DNA methyltransferase inhibitor, as an experimental tool to examine whether LRIG1 expression could be induced in breast cancer cells by CpG island demethylation." (PMID 35440669, 2022). "LRIG1 gene expression, protein abundance, and methylation enrichment were examined by quantitative reverse-transcription PCR, immunoblotting, and methylation immunoprecipitation, respectively, in breast cancer cell lines in vitro." (PMID 35440669, 2022). "Interestingly, a recent study using canine mammary tumours as a model for human breast cancer, identified hypermethylation in the third intron of LRIG1 overlapping with a tumour suppressive PAX5 DNA binding motif." (PMID 35440669, 2022). "Interestingly, a proposed molecular mechanism involved in the down-regulation of LRIG1 in breast cancer is mediated by HER2 itself." (PMID 34359928, 2021). "In breast cancer, the regulation of LRIG1 expression and its impact on tumor cell fate are complex." (PMID 32448168, 2020). "The LRIG1 gene has shown both increased and decreased copy numbers in breast cancer." (PMID 32448168, 2020). "LRIG1 suppresses epithelial-to-mesenchymal transition and invasion of basal-like breast cancer cells; however, LRIG1 is downregulated by unknown mechanisms in the majority of basal-like tumors." (PMID 32448168, 2020). "In ER-positive and lymph node-negative breast cancer, LRIG1 mRNA expression is correlated with prolonged relapse-free survival, and in a series of mixed breast cancer cohorts, low expression of LRIG1 was correlated with a shorter distant metastasis-free survival (MFS) and overall survival (OS)." (PMID 32448168, 2020). "However, in a more recent study of stage I-II patients, which utilized a molecular inversion probe analysis platform, only 3.9% of the breast cancers showed an increased LRIG1 copy number, whereas 8.9% showed losses." (PMID 32448168, 2020). "Moreover, an amplicon close to the LRIG1 locus with the coordinates 60M-64M was recently described in breast cancer cell line MCF-7." (PMID 16168117, 2005). "Importantly, our data show that neighborhood deprivation may influence breast cancer outcomes through downregulation of LRIG1 because this tumor suppressor gene is a disease survival–associated gene." (PMID 37930698, 2023). "However, studies on LRIG1 gene methylation in breast cancer remain limited." (PMID 35440669, 2022). "Indeed, LRIG1 mRNA expression might be an independent prognostic marker in different subtypes of breast cancer." (PMID 32448168, 2020). "Thus, the frequencies of LRIG1 gains, losses, and breaks in breast cancer remain controversial." (PMID 32448168, 2020). "Thus, LRIG1 may be an influential determinant of all the major subtypes of breast cancer, including ER-positive, ERBB2-positive, and basal-like breast tumors." (PMID 32448168, 2020). "Additionally, LRIG1 seems to play an important role in basal-like breast cancer." (PMID 32448168, 2020).
breast carcinoma (continued). "The four LRIG1/reference gene ddPCR assay pairs that had shown the ratios closest to 1 among the samples from the healthy individuals were thereafter used to analyze DNA from 34 breast cancer tumors that had been analyzed for LRIG1 copy number variations by FISH in a previous study." (PMID 32448168, 2020). "In a cross-sectional study of 185 women with breast cancer, higher neighborhood deprivation was associated with decreased methylation and gene expression of 2 tumor suppressor genes, LRIG1 and WWOX, for Black patients with breast cancer." (PMID 37930698, 2023). "Methylation of both elements inversely correlates with LRIG1 gene expression, in the TCGA-BRCA cohort and in multiple cell line models of endocrine-resistant breast cancer." (PMID 35440669, 2022). "Thus, LRIG1 gene aberrations may be important biological determinants of various aspects of breast cancer biology, and considered as prognostic markers, but the role of this gene as an independent predictor of relapse in breast cancer appears uncertain." (PMID 32448168, 2020). "Although LRIG1 gene aberrations may be important determinants of breast cancer biology, and prognostic markers, the results of this study do not verify an important role for LRIG1 copy number analyses in predicting the risk of relapse in early-stage breast cancer." (PMID 32448168, 2020). "Hypermethylation at this region correlated with reduced LRIG1 gene expression, which was conserved (along with PAX5-binding motifs) in human breast cancer, suggesting that methylation of LRIG1 in cancer may be a species-conserved mechanism of repression." (PMID 35440669, 2022). "Thus, whereas LRIG1 suppresses ERBB2 expression and the proliferation of ERBB2-positive breast cancer cells, ERBB2 itself downregulates LRIG1 levels in breast cancer cells, thereby canceling the tumor-suppressive function of LRIG1." (PMID 32448168, 2020). "So in estrogen receptor (ER)-positive breast cancer, LRIG1 seems to participate in a negative feedback loop wherein estrogen signaling upregulates LRIG1 expression, which leads to the suppression of cancer cell proliferation." (PMID 32448168, 2020). "LRIG1 also inhibits EMT and invasion of basal-like breast cancer cell." (PMID 30487162, 2019). "The combination of increased LRIG1 copy number and protein expression and low EGFR/ERBB1 expression might represent a subtype of breast cancer with its own clinical features." (PMID 16168117, 2005). "We next went on to test the combination of Panobinostat and ADC, finding this was not consistently superior to ADC alone (except in HCC1937 cells); suggesting that methylation, not deacetylation, is the dominant epigenetic mechanism of LRIG1 silencing in breast cancer." (PMID 35440669, 2022). "Another shortcoming of our study was that our clinical material did not comprise mRNA, and therefore LRIG1 mRNA expression analysis could not be performed to clarify its potential role as a prognostic factor in breast cancer." (PMID 32448168, 2020). "Furthermore, methylation of LRIG1 is increased in primary tumours and lymph node metastases of patients with basal breast cancer/TNBC relative to normal tissue (data from GSE78758), suggesting methylation-mediated silencing of LRIG1 may be important in breast cancer progression." (PMID 35440669, 2022).
glioblastoma (16 papers, 2014 to 2025). The most malignant astrocytic tumor (WHO grade IV). "In the brain, it was shown that LRIG1 inhibits EGFR expression in glioblastoma cells by causing the activation of downstream signaling pathways." (PMID 38790164, 2024). "Here, we perform gain- and loss-of-function studies to understand the function of Lrig1 in glioblastoma stem cells." (PMID 36420140, 2022). "Previous studies associated LRIG1 with brain cancer, where it inhibits EGFR expression in glioblastoma cells." (PMID 38790164, 2024). "In contrast, Lrig1 overexpression in mouse glioblastoma stem cells results in enhanced quiescence and reduced proliferation, with impaired tumour formation upon orthotopic transplantation." (PMID 36420140, 2022). "Using a novel mouse glioblastoma stem cell model, we show that genetic ablation of Lrig1 in cultured GBM stem cells results in higher proliferation and loss of quiescence." (PMID 36420140, 2022). "Elevated miR-183 contributes to the radioresistance of glioblastoma through decreasing LRIG1 expression." (PMID 32943988, 2020). "Previous research corroborated the decrease in LRIG1 in glioblastoma cells upon hypoxia conditions, and its enhancement inhibited tumor growth and cell migration." (PMID 30487162, 2019). "Previously, we demonstrated that overexpression of full-length LRIG1 inhibited the growth of glioblastoma cells in vitro." (PMID 25353163, 2014). "In fact, the findings of previous reports have shown that LRIG1 is downregulated in several types of tumors, such as cutaneous squamous cell carcinoma, renal cell carcinoma, glioblastoma, and breast cancer." (PMID 24709893, 2014). "Further, secondary glioblastoma expressed more LRIG1 protein than primary." (PMID 41201961, 2025). "In glioblastoma, LRIG1 silencing promotes cell proliferation and invasion." (PMID 30487162, 2019). "Therefore the mechanisms underlying the function differences between LRIG2 ectodomain and LRIG1 ectodomain in the progression of glioblastoma are needed to be further addressed in the future." (PMID 25353163, 2014). "Intriguingly, the other human glioblastoma cell line, TB101, exhibited contrary behaviors when LRIG1 was overexpressed, i.e., its migration rate was unaltered whereas its proliferation rate was reduced." (PMID 29391393, 2018). "In vivo, mice transplanted with glioblastoma stem cells lacking Lrig1 display lower survival compared to Lrig1 WT glioblastoma stem cells, with tumours displaying increased proportions of proliferative cells and reduced quiescent subpopulations." (PMID 36420140, 2022). "To this end, we transduced two human high-grade glioblastoma cell lines, TB101 and TB107, with lentiviral vectors expressing either LRIG1 (pLVX-LRIG1) or empty control vector (pLVX-Puro) and assessed the behavior of the transduced cells in immunocompromised mice in vivo." (PMID 29391393, 2018). "As previous study demonstrated that soluble LRIG1 ectodomains could be released from the full-length LRIG1, we wanted to address whether soluble LRIG2 ectodomains could be released from glioblastoma cells." (PMID 25353163, 2014).